EGFR (epidermal growth factor receptor)
Diseases named in the same sentence as EGFR in open-access papers (continued):
Sharing a sentence is not in itself a finding about the gene and the disease.
colorectal cancer (continued). "Finally, expression data from seven NSCLC and one colorectal cancer (primary and metastatic tumours), paraffin-embedded tumour samples from patients treated with EGFR inhibitors were also tested." (PMID 22045191, 2012). "No significant response to therapy with anti-EGFR antibodies have been observed in colorectal cancer patients exhibiting KRAS mutations." (PMID 22931052, 2012). "The lack of benefit from anti-EGFR monoclonal antibodies in colorectal cancer patients with K-RAS mutations has been demonstrated." (PMID 27398239, 2012). "Thus, EGFR downregulation is a critical target for therapy against colorectal cancer that is highly dependent on EGFR." (PMID 22788833, 2012). "Although in colorectal cancer patients K-RAS mutations represent a validated negative predictive biomarker for treatment with anti-EGFR monoclonal antibodies, their role in selecting specific treatment for NSCLC patients remains undefined." (PMID 27398239, 2012). "In CAIRO2 (capecitabine, irinotecan, and oxaliplatin in advanced colorectal cancer) and PACCE (panitumumab advanced colorectal cancer evaluation study) trials, the addition of anti-EGFR antibody to a combination of chemotherapy and bevacizumab significantly reduced the PFS." (PMID 23097702, 2012). "Indeed, chemotherapy with cetuximab or panitumumab, both of which are also anti-EGFR monoclonal antibodies, can prolong survival period of colorectal cancer patients by nearly twenty-four months." (PMID 22788833, 2012). "Targeted treatment of colorectal cancer has also been limited by resistance to anti-EGFR therapy." (PMID 23198146, 2012). "KRAS mutations only accounts for 30-40% of the non-responders to EGFR targeted MoAbs in colorectal cancer." (PMID 21439039, 2011). "The expanding role of anti-EGFR therapeutic modalities for the treatment of colorectal cancer patients, along with the growing number of cases potentially requiring such a treatment approach, made the need for a correct and reliable identification of responding tumours increasingly crucial." (PMID 21559018, 2011). "CONCLUSION:EGFR promoter hypermethylation, after confirmation in larger data set, may represent a valuable asset in further studies investigating EGFR as a therapeutic target in colorectal cancer." (PMID 21559018, 2011). "Epidermal growth factor receptor (EGFR), a receptor tyrosine kinase whichpromotes cell proliferation and survival, is abnormally overexpressed innumerous tumors of epithelial origin, including colorectal cancer (CRC)." (PMID 21464950, 2011). "Hence, there are still many questions that need to be answered before we can fully understand the impact of the EGFR signaling pathway on colorectal carcinogenesis and the prognosis of patients with colorectal cancer." (PMID 21403829, 2011). "The wide range of EGFR expression in colorectal cancer reported in the literature, as well as the uncertain significance of EGFR expression as a prognostic indicator, may be related to the methodology used to detect EGFR." (PMID 21403829, 2011). "Similarly, stimulation of oxaliplatin-DNA adduct formation has previously been correlated with the potentiation of oxaliplatin cytotoxicity by the anti-EGFR cetuximab in HCT-8 colorectal cancer cells." (PMID 21970874, 2011). "Colorectal cancers lacking oncogenic alterations in genes encoding EGFR downstream effectors such as KRAS, BRAF, PIK3CA, and PTEN have the highest probability of response to anti-EGFR therapies." (PMID 22152101, 2011). "Most studies use immunohistochemistry to detect EGFR expression in colorectal cancers." (PMID 21403829, 2011). "Several groups have recently validated that KRAS mutations are a negative predictor of colorectal carcinoma response to monoclonal antibodies (e.g. panitumimab and cextuximab) targeting epidermal growth factor receptor (EGFR)." (PMID 21738606, 2011).
colorectal cancer (continued). "Although IHC analysis of EGFR in colon cancers does not predict the efficacy of anti-EGFR antibody therapy, the potential predictive impact of phospho-EGFR expression for anti-EGFR antibodies in human colorectal cancers remains unknown." (PMID 19997103, 2010). "In addition, although we cannot generalize, longstanding experience of EGFR in colorectal cancer as a target and molecular predictor of EGFR inhibitors should be considered before talking about novel targets in medical oncology." (PMID 21078151, 2010). "Disturbed EGFR signalling, due for example to the overexpression of EGFR, is involved in the pathogenesis of several cancer types, and antibodies directed towards the extracellular domain of EGFR have been developed for the treatment of cancers such as advanced colorectal cancer." (PMID 21203460, 2010). "Recently a number of randomized trials have shown that patients with advanced colorectal cancer do not benefit from therapies targeting the epidermal growth factor receptor when their tumors harbor mutations in the KRAS, BRAF and PIK3CA genes." (PMID 20098682, 2010). "Mutational analysis of the KRAS gene has recently been established as a complementary in vitro diagnostic tool for the identification of patients with colorectal cancer who will not benefit from anti-epidermal growth factor receptor (EGFR) therapies." (PMID 20385028, 2010). "However, only limited data exist for phospho-EGFR in human colorectal cancers and highly variable expression frequencies were reported using an anti-Tyr 1068 antibody." (PMID 19997103, 2010). "Moreover, anti-HER1 (EGFR) mAb, Cetuximab, has now been approved for use in patients with colorectal cancer." (PMID 20029417, 2010). "Of these agents, epidermal growth factor receptor (EGFR) inhibitors have played a visible role in the management of solid malignancies including colorectal cancer, metastatic non small-cell lung cancer (NSCLC), pancreatic cancer, and squamous-cell carcinoma of the head and neck (HNSCC)." (PMID 19636422, 2009). "However, EGFR gene amplification has been reported to be positively associated with response to EGFR-directed antibody therapies in clinical trials for nonsmall lung cancers (NSCLC) and colorectal cancers." (PMID 19636423, 2009). "For the first time in literature, we show that primary colorectal cancer and paired metastasis may exhibit difference with respect to EGFR pathway deregulation mechanisms possibly implying a different response to cetuximab or panitumumab treatment." (PMID 19293803, 2009). "FISH and CISH EGFR GCN may both represent effective tools for a further patients selection in K-RAS wild-type colorectal cancer treated with cetuximab." (PMID 19712476, 2009). "It plays a key role in the RAS/MAPK signally pathway located downstream ofmany growth factor receptors, including EGFR, and involved in carcinogenesis.Mutations of KRAS that result in the constitutive activation of MAPK pathwaydownstream occurs in about 40% of colorectal cancers." (PMID 19365583, 2009). "It has become clear that patients with colorectal cancer whose tumor has an activating mutation in KRAS do not respond to monoclonal antibody therapies targeting EGFR." (PMID 19386128, 2009). "Also, PGE2-dependent EGFR activation in human colorectal cancer cells appears to be variable, with responsive (LS-174) and unresponsive (DLD-1) cell lines described." (PMID 19055708, 2008). "In conclusion, synchronous and metachronous liver metastases from colorectal cancer have a different gene expression signature and a different expression of EGFR and COX-2 that may be the basis for choosing the medical treatment." (PMID 18827815, 2008). "We analysed the expression of activated (phosphorylated) Akt and MAPK in 98 cases of paired primary colorectal tumours and metastases with the aim to define better the epidermal growth factor receptor (EGFR)-related molecular profile of colorectal cancer as a tool for treatment selection." (PMID 17579627, 2007).
colorectal cancer (continued). "In colorectal cancer (CRC), it is well documented that EGFR expression may be associated with an advanced disease stage." (PMID 17311026, 2007). "We then analysed the expression of activated (phosphorylated) Akt and MAPK in primary tumours and the corresponding metastatic sites with an already known EGFR status, with the aim to define better the EGFR-related molecular profile of colorectal cancer, to serve as a tool for treatment selection." (PMID 17579627, 2007). "We then analysed the expression of activated (phosphorylated) Akt and MAPK in primary tumours and corresponding metastatic sites with an already known EGFR status, with the aim to define better the EGFR-related molecular profile of colorectal cancer, to serve as a tool for treatment selection." (PMID 17579627, 2007). "The current is a retrospective study that specifically investigated whether adjuvant chemotherapy could influence the status of EGFR staining in recurrent colorectal cancer." (PMID 17163999, 2006). "This study investigates whether postoperative adjuvant therapy affects the degree of concordance between EGFR statuses of the primary and recurrent colorectal cancer." (PMID 17163999, 2006). "In colorectal cancer, EGFR expression was evaluated in resected tumors." (PMID 15967033, 2005). "Therefore, our results detected a low percentage of EGFR immunopositivity (56%) as compared with other colorectal cancer trials probably due to the numerous IHC techniques." (PMID 15967033, 2005). "However, in refractory colorectal cancer, EGFR immunohistochemical overexpression, with a rate of 1% tumoral positive cells for a positive score, did not predict response to this therapy." (PMID 15986037, 2005). "Phase III trials should elucidate whether capecitabine may become the backbone of colorectal cancer combination therapy, not only with irinotecan, oxaliplatin and radiotherapy but also with novel agents such as EGFR inhibitors and anti-angiogenic agents." (PMID 15026800, 2004). "In the present study, we evaluated the potential influence of ZD1839 on the radiation response of the human colorectal carcinoma cell line LoVo which has moderate levels of EGFR expression (33 000 receptors per cell), and is therefore likely to be representative of most epithelial tumour cell lines." (PMID 11953865, 2002). "Therefore, this study aimed to comprehensively characterize fluorescence kinetics, background clearance, and EGFR-dependent tumor uptake in colorectal cancer models to establish a solid preclinical foundation for colorectal-specific clinical translation of cetuximab-IRDye800CW." (PMID 41346398, 2025). "After a multidisciplinary review by our oncology team, it was determined that the malignancy might be susceptible to BRAF and MEK inhibition, as well as their combination with anti-EGFR antibody therapy, following the same rationale as BRAF mutation-positive colorectal cancer." (PMID 40688855, 2025). "Interestingly, the selection of EGFR‐overexpressing tumors was not effective in identifying colorectal cancers as susceptible of pharmacological blockade of the receptor." (PMID 39470386, 2025). "While its role in OA remains unclear, evidence from studies on colorectal cancer suggests that TSPAN8 modulates cell motility by linking epidermal growth factor receptor (EGFR) signaling to integrin/TLR-mediated pathways; EGFR silencing was found to enhance migration in TSPAN8-expressing cells." (PMID 41146237, 2025). "Notably, suppression of EGFR, SRC, STAT3, and AKT1, which are implicated in both inflammation and carcinogenesis, opens avenues for investigating BRLE in chemoprevention of colitis-associated colorectal cancer." (PMID 41465478, 2025). "Targeted therapy for BRAF-mutated colorectal cancer has evolved from conventional anti-VEGF/anti-EGFR based regimens to BRAF targeted therapy; however, none achieved substantial clinical benefits until the BEACON trial established the efficacy of dual EGFR/BRAF inhibition." (PMID 41355781, 2025).
colorectal cancer (continued). "Vascular endothelial growth factor receptor-2 (VEGFR-2) and epidermal growth factor receptor (EGFR) belong to the family of tyrosine kinase receptors (RTKs), which are frequently mutated and/or overexpressed in different kinds of human cancers, namely lung, breast, and colorectal carcinoma." (PMID 39942770, 2025). "Furthermore, we are currently designing a targeted delivery system for this stable IL-10 isoform by conjugating it to tumor-specific antibodies (e.g., anti-EGFR) to improve intratumoral accumulation and therapeutic efficacy in preclinical models of colorectal carcinoma." (PMID 40149345, 2025). "Notably, FOXK2’s regulation on EGFR can be context-dependent and cell-specific; it functions as a tumor suppressor gene in ccRCC by inhibiting EGFR and inducing apoptosis, contrasting its role in colorectal cancer." (PMID 38741782, 2024). "It remains unclear whether intensification of the chemotherapy backbone in tandem with an anti-EGFR can confer superior clinical outcomes in a cohort of RAS/BRAF wild-type colorectal cancer (CRC) patients with initially unresectable colorectal liver metastases (CRLM)." (PMID 38728364, 2024). "The potential interplay or distinct impact of mutations within the EGFR pathway (EGFR, KRAS, NRAS, BRAF, PI3KCA), along with polymorphisms in genes related to 5-fluorouracil and oxaliplatin (DPYD, TYMS, GSTP1, MTHFR, ABCB1), on the prognosis of colorectal cancer remains uncharted territory." (PMID 38248103, 2024). "Similarly, we found a positive correlation between B7-H3 and EGFR in colorectal cancer cell lines." (PMID 38370387, 2024). "Our previous study demonstrated that ACEA‐induced CB1 activation could suppress M2 macrophage expression in colorectal cancer by downregulating epidermal growth factor receptor (EGFR), and it could downregulate the expression of IL‐10, CCL22, Arg‐1, and CD206 in the TME." (PMID 38350727, 2024). "Despite the development of EGFR antibodies, such as cetuximab and panitumumab, as targeted therapies for colorectal carcinoma (CRC), the clinical outcomes have presented challenges." (PMID 38844562, 2024). "Cetuximab is a monoclonal antibody that targets the epidermal growth factor receptor (EGFR) and has been extensively studied for the treatment of metastatic colorectal carcinoma (CRC)." (PMID 39618678, 2024). "It must be noted that this is an acute increase in KRAS expression, which might have very different effects than KRAS overexpression caused by gene amplification that has been associated with resistance to EGFR and KRAS targeted therapies in colorectal cancer cell lines." (PMID 37627169, 2023). "The suboptimal MAPK signaling with dabrafenib plus trametinib in colorectal cancer may be explained by an epigenetic mechanism including the utilization of epidermal growth factor receptor signaling to maintain BRAF-MEK-ERK signaling in the face of BRAF inhibition." (PMID 37059834, 2023). "Current medical guidelines for colorectal cancers, including National Comprehensive Cancer Network and European Society for Medical Oncology have recently added primary tumor location for cetuximab and panitumumab, anti-EGFR antibodies, in their recommendations for making therapeutic decisions." (PMID 36802389, 2023). "Sankha Bhattacharya’s study showed that polymeric nanoparticles conjugated with anti-EGFR monoclonal antibody and 5-fluorouracil (5-FU) had higher cellular uptake and higher cytotoxicity, and thereby have a good therapeutic effect on EGFR-positive colorectal cancer." (PMID 37009262, 2023). "In addition, FMR1 can promote the development of colorectal cancer cells by stabilizing EGFR mRNA." (PMID 37302999, 2023). "Colorectal cancer with KRAS mutations is a negative marker for anti-EGFR targeted drugs." (PMID 37311935, 2023).
colorectal cancer (continued). "The rapid onset of resistance to epidermal growth factor receptor tyrosine kinase inhibitor (EGFR-TKI) limits its clinical utility in colorectal cancer (CRC) patients, and pan-erb-b2 receptor tyrosine kinase (ErbB) treatment strategy may be the alternative solution." (PMID 35319011, 2022). "The assembly of the IS by a trispecific T cell engager (TriTE) against EGFR, EpCAM, and CD3ε in comparison with two bispecific EGFRxCD3ε and EpCAMxCD3ε LiTEs has been also evaluated under the microscope by co-culturing Jurkat cells with colorectal cancer cells expressing EGFR and EpCAM." (PMID 36678761, 2022). "Thus, our study suggested that CB1 may be a new strategy to suppress EGFR, and serve as a novel target for colorectal cancer treatment." (PMID 35641479, 2022). "However, concurrent treatment with anti-HER2 therapy and anti-EGFR therapy, may overcome this resistance: pertuzumab and lapatinib has demonstrated meaningful activity in patient-derived xenografts of colorectal cancer resistant to cetuximab." (PMID 35565354, 2022). "Therefore, we propose that colorectal cancer patients can be safely treated preoperatively with a low dose of anti-EGFR antibodies to eliminate CTCs, which may ultimately prevent metastasis development." (PMID 35035479, 2022). "Notably, evidence for a possible involvement of ALK in colorectal cancer has already been suggested, mostly arguing for a cross-talk with EGFR and revealing the presence of tumors harboring both tyrosine kinase receptors alteration or ALK gene amplification as a poor prognostic factor." (PMID 35351152, 2022). "These simultaneously deliver an inhibitor of the EGFR tyrosine kinase, and plasmid DNA coding for a Crk-based biosensor, Picchu-X, which when expressed in the target cells can be used to quantify the inhibition of EGFR in vivo in a mouse colorectal cancer xenograft model." (PMID 34730152, 2021). "Similarly, treatment of colorectal cancer with anti-EGFR monoclonal antibodies cetuximab or panitumumab is only successful in a subset of patients due to the appearance of Ras mutations and variations in the EGFR extracellular domain, which reduce antibody binding efficiency, initiating relapse." (PMID 34356110, 2021). "In a large cohort of colorectal cancer patients, ctDNA analysis allowed the identification of actionable gene fusions, including 10 ALK fusion-positive patients; 7/10 samples also carried additional mutations in EGFR, KRAS and NRAS genes and were associated with resistance to anti-EGFR therapy." (PMID 34680298, 2021). "In fact, preclinical and clinical studies have shown that the combination of the anti-EGFR antibody cetuximab with anti-4-1BB agonist leads to tumor resolution and prolonged survival, likely dependent on enhanced NK cell degranulation and cytotoxicity, in head and neck and colorectal cancers." (PMID 33520112, 2021). "Currently, a ctDNA assay for the detection of EGFR mutations in patients with non-small-cell lung cancer (NSCLC) has been approved by the Food and Drug Administration, and ctDNA assays for EGFR in NSCLC and for KRAS in colorectal cancer are available for commercial use in Europe3,4,45." (PMID 33441840, 2021). "Although it has been confirmed that miR-875-5p exerts tumor suppressor function via down-regulation of EGFR in colorectal carcinoma (CRC), the specific functions and relevant machinery of miR-875-5p in ESCC have not been elucidated." (PMID 33505778, 2021). "However, whether FAK participates in EMT in colorectal cancer cells through the EGF/EGFR signaling pathway remains unknown." (PMID 32148496, 2020).